ZNF703 (zinc finger protein 703)
Description:
Transcriptional corepressor which does not bind directly to DNA and may regulate transcription through recruitment of histone deacetylases to gene promoters. Regulates cell adhesion, migration and proliferation. May be required for segmental gene expression during hindbrain development.
Synonyms: ZEPPO1; ZPO1; FLJ14299; ZNF503L; NLZ1
Tractability: No criterion of Open Targets' tractability assessment is met for any kind of drug.
Gene: Protein-coding gene on chromosome 8 (37,695,782 to 37,700,019, forward strand). Ensembl gene ENSG00000183779.
Subcellular location: Nucleus; Cytoplasm
Pathways (Reactome):
Gene expression (Transcription): Generic Transcription Pathway
Gene Ontology:
Molecular function: protein binding; DNA-binding transcription factor binding
Biological process: cellular response to estradiol stimulus; mammary gland epithelial cell differentiation; negative regulation of DNA-templated transcription; positive regulation of cell population proliferation; positive regulation of mammary gland epithelial cell proliferation; regulation of cell cycle; regulation of DNA-templated transcription; regulation of transforming growth factor beta receptor signaling pathway; adherens junction assembly; negative regulation of homotypic cell-cell adhesion; positive regulation of cell migration; positive regulation of epithelial to mesenchymal transition; regulation of canonical Wnt signaling pathway
Cellular component: cytoplasm; mitochondrion; nuclear matrix; nucleus; protein-containing complex
Genetic constraint (gnomAD): Loss-of-function variants: 18 observed, 16.86 expected, observed/expected ratio (o/e) 1.07, 90% interval 0.74 to 1.58. The synonymous counts are far from expectation, so gnomAD's model fits this gene poorly and the ratio says little. Missense variants: 814 observed, 628.99 expected, observed/expected ratio (o/e) 1.29, 90% interval 1.22 to 1.37. Synonymous variants: 457 observed, 324.68 expected, observed/expected ratio (o/e) 1.41, 90% interval 1.3 to 1.52.
Homologues: Orthologues: chimpanzee ZNF703 (99% identical), macaque ZNF703 (99% identical), pig ZNF703 (97% identical), mouse Zfp703 (95% identical), dog ZNF703 (95% identical), rat Zfp703 (95% identical), tropical clawed frog znf703 (65% identical), zebrafish znf703 (56% identical), Drosophila melanogaster noc (26% identical), Drosophila melanogaster elB (23% identical), Caenorhabditis elegans tlp-1 (17% identical). Paralogues in human: ZNF503 (57% identical).
Diseases named in the same sentence as ZNF703 in open-access papers:
ZNF703 is named in the same sentence as 34 diseases in open-access papers, as found by Europe PMC text mining. Sharing a sentence is not in itself a finding about the gene and the disease. The quoted sentences say what the papers report.
breast carcinoma (55 papers, 2012 to 2026). "For ZNF703, GReX was associated with increased breast cancer risk in stromal cells (p value=2.4 × 10−9) and decreased risk in epithelial cells (p value=2.7 × 10−7)." (PMID 36690614, 2023). "ZNF703 amplification, predominantly identified in Luminal B subtype of breast cancer, is associated with poor clinical outcomes." (PMID 35804935, 2022). "ZNF703 amplifications, for example, are associated with PR negativity among ER positive breast cancers." (PMID 32987805, 2020). "ZNF703 is induced 25-fold and is a transcriptional corepressor that is associated with breast cancer." (PMID 33348896, 2020). "Vertebrate NET proteins play an important role in the developing nervous system, and mutations in the homolog ZNF703 human promote luminal breast cancer." (PMID 24625735, 2014). "Taken together, our results support ZNF703 as an oncogene in breast cancer whose high expression predisposes to poor clinical outcome in patients with luminal B tumors." (PMID 24156016, 2013). "Besides luminal B breast tumors, ZNF703 was also reported to have been implicated in infiltrating lobular breast cancer or progression of lobular carcinoma in situ to invasive cancer." (PMID 35236318, 2022). "Furthermore, overexpression of the mouse Znf703 is associated with breast cancer progression and metastasis." (PMID 27929068, 2016). "Further insights into the functional and clinical implications of SPRY4-IT1 and its target ZNF703 may facilitate the identification of novel diagnostic or predictive biomarkers and drug targets for breast cancer." (PMID 25742952, 2015). "Mutations in the human Elb/Noc homolog ZNF703 promote metastasis in luminal breast cancer." (PMID 24625735, 2014). "Loss of one NET family member, ZNF703, in humans promotes luminal breast cancer." (PMID 24625735, 2014). "It has been shown that ZNF703 gene amplification stimulates migration and proliferation while reducing cell to cell adhesion and is speculated to be associated with poorer outcomes in breast cancer." (PMID 26063961, 2015). "The discovery that ZNF703 is a gene that SPRY4‐IT1 targets downstream and the demonstration that ZNF703 increases the growth of ER (−) breast cancer cells and inhibits apoptosis in vivo have both been made." (PMID 41459628, 2026). "From an initial set of 14 ASOs, we identified ASO9 as the most efficient for silencing ZNF703 expression in an engineered breast cancer cell line." (PMID 37514116, 2023). "Another uniquely expressed cell cycle regulatory protein is ZNF703, which is overexpressed in ER/PR-positive breast cancer and promotes tumor cell proliferation and invasion in colorectal cancer." (PMID 37686244, 2023). "Commonly found amplified in luminal B breast cancer, ZNF703 gene overexpression influences several aspects of the pathology of BC, including ER signaling and the phenotypes of progenitor cells." (PMID 37514116, 2023). "We detected the expression of ZNF703 in thirteen breast cancer cell lines and two normal breast epithelial cell lines by western blot." (PMID 35236318, 2022). "ZNF703 overexpression has been attributed to chr8-chr14 translocation in 7 out of 10 breast cancer samples and T47D breast cancer cells." (PMID 35011637, 2021). "Translocations of large portions of chromosome arms have a potential impact on gene expression by TAD alteration; for example, Zinc Finger Protein 703 (ZNF703) is a typical Luminal B breast cancer oncogene that is found on chromosome 8." (PMID 35011637, 2021). "We observed a high frequency (>50%) of copy number gain at three well-known breast cancer loci that contain potential oncogenes (chr8p11.23 [ZNF703] n = 8, 53.3%; chr8q24.2 [MYC] n = 9, 60%; chr19q12 [CCNE1] n = 9, 60%)." (PMID 34535742, 2021). "Recent database publications demonstrated the possible mechanisms of miR-491-5p in suppressing the migration and invasion of breast cancer by targeting ZNF-703 to regulate the AKT/mTOR pathway or via TPX2 targeting." (PMID 34395516, 2021).
breast carcinoma (continued). "Other studies have pointed out that lncRNA-UCA1 can target and regulate zinc finger protein 703, increase its functional activity and enhance the proliferation ability of breast cancer cells." (PMID 33194612, 2020). "ZNF703 was discovered to exert oncogenic function in numerous cancers, such as colorectal cancer, breast cancer and cholangiocarcinoma." (PMID 32351330, 2020). "ZNF703 suppresses also TGFβ signaling in breast cancer cells, neutralizing TGFβ-mediated anti-proliferative transduction signals." (PMID 32987805, 2020). "A survey of genome gains and losses in luminal and basal breast cancers using array comparative genomic hybridization (aCGH) microarrays disclosed that ZNF703 was the most significant candidate oncogene in luminal cancers." (PMID 32987805, 2020). "Breast cancer cell lines expressing ZNF703 were resistant to tamoxifen treatment, while down-regulation of ZNF703 mRNA through miRNA synergized with tamoxifen in cell killing." (PMID 32987805, 2020). "Luminal breast cancer cell lines in which the ZNF703 is overexpressed are seen to be resistant to tamoxifen through the activation of Akt/mTOR signaling." (PMID 29921827, 2018). "SPRY4-IT1 increased the proliferation through upregulation of ZNF703 expression in human breast cancer cells." (PMID 29489909, 2018). "LncRNA SPRY4-IT1 increases proliferative abilities of breast cancer cells through upregulation of zinc finger protein 703 (ZNF703) expression." (PMID 29137412, 2017). "Both Cyclin D1 and ZNF703 were among the genes identified as breast cancer drivers, as were an additional 27 genes with E2-induced R-loops." (PMID 27552054, 2016). "A recent study demonstrated that enhanced ZNF703 expression represses E‐cadherin expression and increases lung metastasis rates in a mouse model of breast cancer." (PMID 27650486, 2016). "Subsequent data demonstrated that ZNF703 overexpression increased lung metastases in a mouse breast cancer model." (PMID 26063961, 2015). "To assess the contribution of ZNF703 to the biological effects of ER(−) breast carcinoma, we evaluated the impact of ZNF703 silencing and overexpression on cell proliferation and apoptosis in MDA-MB-231 and MDA-MB-435S cells." (PMID 25742952, 2015). "Our results reveal that the effect of SPRY4-IT1 on breast cancer is at least in part through targeting ZNF703." (PMID 25742952, 2015). "A recent study demonstrated that enhanced ZNF703 expression represses E-cadherin expression and increases lung metastases in a mouse model of breast cancer." (PMID 25742952, 2015). "The function of ZNF703 in ER(−) breast carcinoma cells was manipulated with small interfering RNAs (siRNAs) in MDA-MB-231 and MDA-MB-435S cells." (PMID 25742952, 2015). "To further confirm that ZNF703 is involved in the SPRY4-IT1-induced increase in breast cancer cell proliferation, we performed rescue experiments." (PMID 25742952, 2015). "Earlier studies also showed that ZNF703 stimulated mammary epithelial cells toward immortalization rather than differentiation and enhanced the invasive potential of breast cancer cells." (PMID 26063961, 2015). "ZNF703, like FGFR1, is localized at the 8p11 locus and there is compelling evidence that ZNF703 is one of the driver genes in this amplified region, especially in breast cancers where ZNF703 expression seems to be induced by estrogens." (PMID 25596748, 2015). "ZNF703, a gene that plays an oncogenic role in luminal B type breast cancer, is likely the most functionally important gene in the 8p12 amplicon." (PMID 25742952, 2015). "Overexpression of ZNF703 was also found in other cancers, such as breast cancer, gastric cancer, and colorectal cancer." (PMID 26063961, 2015). "Taken together, these results suggest that ZNF703 can promote the proliferation and suppress the apoptosis of ER(−) breast cancer cells in vivo." (PMID 25742952, 2015).
breast carcinoma (continued). "We found that ZNF703 overexpression partially compromised the effects of SPRY4-IT1 on breast cancer proliferation, whereas the knockdown of ZNF703 had the opposite effects." (PMID 25742952, 2015). "Consistently, the TUNEL staining results also showed that ZNF703 overexpression partially compromised the effects of knockdown of SPRY40-IT1 on breast cancer apoptosis, whereas the knockdown of ZNF703 had the opposite effects." (PMID 25742952, 2015). "In this study, we provide the first demonstration that ZNF703plays an oncogenic role in ER (−) breast carcinoma cells and that the expression level of ZNF703 is higher in MDA-MB-231 and MDA-MB-435S cells compared with human breast epithelial cells (MCF-10A)." (PMID 25742952, 2015). "ZNF703 overexpression in MCF-7 breast cancer cells activated the Akt/mTOR signaling pathway, downregulated ERα, and reduced the antitumor effect of tamoxifen." (PMID 23991038, 2013). "IHC was used to evaluate ZNF703 expression in the breast cancer specimens, and high ZNF703 was mainly found in luminal breast cancers." (PMID 23991038, 2013). "The modes of tamoxifen action were distinct between breast cancer cell lines with high or low ZNF703 expression." (PMID 23991038, 2013). "We used immunohistochemistry techniques to examine ZNF703 expression in stage I-III primary breast cancer specimens and found a positive expression rate of 91.3%." (PMID 23991038, 2013). "ZNF703 is overexpressed in some breast cancer cell lines, but has low expression in normal mammary epithelial cells." (PMID 23991038, 2013). "We suggest ZNF703 as a candidate for a marker of worse prognosis, in particular for women with luminal B breast cancer." (PMID 24156016, 2013). "We assessed ZNF703 expression in clinical breast cancer specimens, and used breast cancer cell lines to investigate the role of and underlying mechanisms of ZNF703 in endocrine therapy." (PMID 23991038, 2013). "These functions suggest that ZNF703 plays an important role in breast cancer formation and progression." (PMID 24156016, 2013). "Given the involvement of ZNF703 in luminal-type breast cancer, we assessed ZNF703 mRNA expression levels in breast cancer cell lines by real time and reverse transcription polymerase chain reaction (RT-PCR)." (PMID 23991038, 2013). "ZNF703 was recently identified as a novel breast cancer oncogene in the 15% of breast cancers that harbor 8p12 amplifications, amplified second only to the well-known oncogenes, ERBB2 and cyclin D1 (CCND1)." (PMID 23991038, 2013). "Two studies, in which a large number of breast tumors were used, demonstrated that ZNF703 meets the criteria as the genetic driver of the A1 amplicon, emerging as a gene with an oncogenic role in luminal B type breast cancer 16–17." (PMID 24156016, 2013). "Next, we performed experiments to determine if ZNF703 impacted 4-hydroxytamoxifen (TAM) sensitivity in breast cancer cell lines." (PMID 23991038, 2013). "Amplification was observed over cancer genes previously implicated in breast cancer development including ERBB2, CCND1, MYC, MDM2, ZNF217, and ZNF703 and a homozygous deletion involving MAP2K4 was identified." (PMID 22608084, 2012). "Furthermore, H19 has been shown to regulate the expression of miR-491-5p and inversely modulate ZNF703, playing a critical role in breast cancer development." (PMID 38166752, 2024). "Amplification of (the region surrounding) ZNF703 was not described for HER2+ breast cancer, but has been linked to luminal B breast cancer before, which is known to be inherently aggressive." (PMID 37968696, 2023). "MCF7-ZNF703/GFP was chosen because it is a luminal breast cancer cell line in which ZNF703 was artificially overexpressed leading to various consequences including cell proliferation and resistance to tamoxifen previously reported and known to reflect luminal B phenotype." (PMID 37514116, 2023). "MDA-MB-134 is a luminal B breast cancer cell line with the highest ZNF703 mRNA expression." (PMID 37514116, 2023).
breast carcinoma (continued). "In another study, which explored the associations between gene mutations and clinicopathologic characteristics by FoundationOne CDx assay in a cohort of 223 clinically advanced breast cancers, ZNF703 gene alterations were enriched in 7.2% of locally advanced TNBCs, but not in metaplastic TNBCs." (PMID 35236318, 2022). "Upregulated SPRY4-IT1 (SPRY4 intronic transcript 1) promotes the proliferation of human breast cancer cells by increasing the expression of the transcription corepressor ZNF703 (zinc finger 703), which may function as an oncogene in breast carcinoma cells." (PMID 33291485, 2020). "Interrogation of TCGA breast cancer cohort confirmed that the 11q13 amplification (as captured by amplification of CCND1 gene) is observed in 34.7% of cases with the 8p11.23 amplicon (as represented by amplification of ZNF703 gene)." (PMID 32987805, 2020). "In addition, SPRY4-IT1 also demonstrated the oncogenic role via targeting zinc finger protein 703 in breast cancer and ESCC." (PMID 28410241, 2017). "ZNF703 was identified as the driver of 8p12 locus amplication in breast cancer development." (PMID 28038461, 2017). "ZNF703 may act as an oncogene in only a subset of the tumors as has been reported for breast cancer." (PMID 27650486, 2016). "Moreover, we provide the first demonstration that ZNF703 plays an oncogenic role in ER (−) breast carcinoma cells." (PMID 25742952, 2015). "Interestingly, high expression of ZNF703 has been shown to correlate with poor prognosis in patients with luminal B breast cancer." (PMID 25994056, 2015). "First, we assessed ZNF703 expression in three human breast cancer cell lines by qRT–PCR." (PMID 25742952, 2015). "ZNF703 has been identified as a novel oncogene in human breast cancer." (PMID 25742952, 2015). "We found that high ZNF703 expression mainly occurred in ER+ and PR+ breast cancers." (PMID 23991038, 2013). "In addition, overexpression of ZNF703 correlated with an intermediate grade, suggesting a moderate prognosis in breast cancer." (PMID 23991038, 2013). "We examined ZNF703 expression in breast cancer tissue microarray." (PMID 23991038, 2013). "ZNF703 is a novel oncogene in the 15% of breast cancers that harbor 8p12 amplifications." (PMID 23991038, 2013). "However, further studies are needed to verify if ZNF703 is negatively correlated with ER expression in breast cancer patients." (PMID 23991038, 2013). "In 127 breast cancer patients, the positive expression rate of ZNF703 protein was 91.3%." (PMID 23991038, 2013). "Furthermore, 4-hydroxytamoxifen had different modes of action in breast cancer cell lines with high or low ZNF703 expression." (PMID 23991038, 2013). "Importantly, MiXcan uniquely identified three novel breast cancer susceptibility genes (ZNF703, TMEM245, and PSG4) that were not previously implicated by breast cancer GWAS11–13 nor TWAS14–16,32." (PMID 36690614, 2023). "However, it is currently unclear whether ZNF703 has similar prognostic power in ER(−) breast carcinoma." (PMID 25742952, 2015). "However, few studies have examined the biological function of ZNF703 in ER (−) breast carcinoma." (PMID 25742952, 2015). "Nevertheless, ZNF703 is still largely unknown in the breast cancer field; for example, it remains to be determined how the expression or function of the encoded protein can be regulated, and the major downstream effectors of its oncogenic functions have not been identified." (PMID 23991038, 2013). "In breast cancer, miR-491-5p suppresses metastasis through ZNF-703 to regulate AKT/mTOR pathway, suggesting miR-491-5p and ZNF-703 as potential therapeutic targets for this tumor type." (PMID 37369946, 2023). "Zinc finger protein 703 (ZNF703), a member of the zinc finger transcription factor Net/NLZ family, abnormally highly expressed in liver cancer, ovarian cancer, breast cancer, and head and neck squamous cell carcinoma." (PMID 37821882, 2023).